BMP6 (bone morphogenetic protein 6)
Description:
Growth factor of the TGF-beta superfamily that plays essential roles in many developmental processes including cartilage and bone formation. Also plays an important role in the regulation of HAMP/hepcidin expression and iron metabolism by acting as a ligand for hemojuvelin/HJV. Also acts to promote expression of HAMP, potentially via the interaction with its receptor BMPR1A/ALK3. Initiates the canonical BMP signaling cascade by associating with type I receptor ACVR1 and type II receptor ACVR2B. In turn, ACVR1 propagates signal by phosphorylating SMAD1/5/8 that travel to the nucleus and act as activators and repressors of transcription of target. Can also signal through non-canonical pathway such as TAZ-Hippo signaling cascade to modulate VEGF signaling by regulating VEGFR2 expression.
Synonyms: VGR; VGR1; IO
Tractability: Small molecule: it has a binding pocket of medium quality. Antibody: UniProt places it where antibodies can reach, with high confidence; UniProt predicts a signal peptide or a membrane-spanning region; its Gene Ontology location is reachable by antibodies, with medium confidence. PROTAC: a small molecule that binds it is known.
Target class: Enzyme; Metallo protease M12A subfamily; Metallo protease; Protease; Metallo protease MAM clan
Gene: Protein-coding gene on chromosome 6 (7,726,049 to 7,881,728, forward strand). Ensembl gene ENSG00000153162.
Subcellular location: Secreted
Subcellular location (Human Protein Atlas): Mitochondria; Predicted to be secreted
Gene Ontology:
Molecular function: BMP receptor binding; cytokine activity; protein binding; protein heterodimerization activity; growth factor activity
Biological process: BMP signaling pathway; bone development; cellular response to BMP stimulus; immune response; intracellular iron ion homeostasis; multicellular organismal-level iron ion homeostasis; negative regulation of adherens junction organization; negative regulation of cell-cell adhesion mediated by cadherin; positive regulation of aldosterone biosynthetic process; positive regulation of bone mineralization; positive regulation of epithelial cell proliferation; positive regulation of gene expression; positive regulation of intracellular signal transduction; positive regulation of osteoblast differentiation; positive regulation of SMAD protein signal transduction; positive regulation of transcription by RNA polymerase II; positive regulation of vascular permeability; type B pancreatic cell development; cellular response to iron ion; heart development; negative regulation of transcription by RNA polymerase II; positive regulation of cell population proliferation; positive regulation of lipopolysaccharide-mediated signaling pathway; positive regulation of protein secretion; skeletal system development; and 19 more
Cellular component: extracellular region; protein-containing complex; vesicle
Genetic constraint (gnomAD): Loss-of-function variants: 17 observed, 48.8 expected, observed/expected ratio (o/e) 0.35, 90% interval 0.24 to 0.52. The upper end of that interval is the gene's LOEUF score, 0.52, which puts it in group 2 of 6, group 1 being the genes least tolerant of losing a copy. Missense variants: 699 observed, 651.13 expected, observed/expected ratio (o/e) 1.07, 90% interval 1.01 to 1.14. Synonymous variants: 317 observed, 266.94 expected, observed/expected ratio (o/e) 1.19, 90% interval 1.08 to 1.3.
Homologues: Orthologues: chimpanzee BMP6 (99% identical), macaque BMP6 (96% identical), mouse Bmp6 (90% identical), rat Bmp6 (90% identical), guinea pig BMP6 (88% identical), pig BMP6 (87% identical), dog BMP6 (83% identical), rabbit BMP6 (66% identical), tropical clawed frog bmp6 (65% identical), zebrafish bmp6 (55% identical). Paralogues in human: BMP5 (53% identical), BMP7 (52% identical), BMP8A (41% identical), BMP8B (41% identical), BMP2 (25% identical), BMP4 (24% identical), GDF2 (22% identical), GDF5 (22% identical), GDF6 (21% identical), BMP10 (21% identical), GDF7 (20% identical), GDF11 (19% identical), and 19 more.
Diseases named in the same sentence as BMP6 in open-access papers:
BMP6 is named in the same sentence as 198 diseases in open-access papers, as found by Europe PMC text mining. Sharing a sentence is not in itself a finding about the gene and the disease. The quoted sentences say what the papers report.
breast cancer (48 papers, 2007 to 2025). A primary or metastatic malignant neoplasm involving the breast. "Associations between decreased BMP6 expression and tumorigenesis, high malignant potential, and/or poorer survival were reported in patients with breast cancer, gastric cancer, and NSCLC, whereas opposite associations were reported in prostate cancer." (PMID 41259663, 2025). "Low BMP6 expression showed correlation with the risk of Relapse Free Survival in breast cancer patients." (PMID 27113436, 2016). "Polymorphisms in BMP6 were independently associated with risk for sickle cell osteonecrosis, pulmonary hypertension in sickle cell disease, breast cancer growth and progression." (PMID 25121767, 2014). "TCGA data analysis demonstrated that mRNA expression of BMP2 and BMP6 are significantly downregulated in breast cancer patients when compared to normal breast tissue." (PMID 38731813, 2024). "The biological characteristics of MMP1 in various cancers have been recognized 43-45; for instance, downregulation of MMP1 by BMP-6 can inhibit tumor metastasis in breast cancer." (PMID 39629135, 2024). "For example, BMP2 and BMP6 inhibit cell proliferation whilst BMP7 promotes the proliferation of breast cancer cells." (PMID 37333824, 2023). "Immunohistochemical studies on patients suggest that bone morphogenetic protein-6 (BMP-6) suppresses breast cancer metastasis." (PMID 36677584, 2023). "BMP-6 inhibited the migration and invasion of breast cancer MDA-MB-231 cells, and this effect was attenuated by overexpression of MMP1." (PMID 36677584, 2023). "Likely in breast cancer, bone morphogenetic protein 6 (BMP6) competitively binds to the miR-21 promoter through the E2-box- and AP-1-binding sites, leading to inhibition of the expression of miR-21 and enhancing E-cadherin to achieve EMT inhibition." (PMID 35805066, 2022). "In breast cancer, as a tumor suppressor gene, BMP6 played an important role in the proliferation, differentiation and chemoresistance of breast cancer cells." (PMID 36532723, 2022). "In breast cancer cells, BMP6 significantly inhibits cell proliferation by reducing the number of cells in the S phase of the cell cycle, thereby blocking tumorigenesis." (PMID 36009721, 2022). "It was showed that BMP6 overexpression promotes invasiveness and migration of prostate and breast cancer cells." (PMID 35163468, 2022). "In the tumor tissues, the BMP6 mRNA or protein expression was significantly correlated with breast cancer tumor grade and ER and PR statuses." (PMID 36532723, 2022). "Previous studies reported that BMP6 played an important role in the occurrence and development of various tumors such as breast cancer, prostate cancer, pleurioma and non-small cell lung cancer (NSCLC)." (PMID 36532723, 2022). "In the context of breast cancer, BMP6, specifically, was shown to inhibit estrogen-dependent cell growth and induce E-cadherin expression in breast cancer cells." (PMID 36078038, 2022). "Specifically, BMP6 signaling leads to downregulation of ZEB1 and preservation of epithelial features in breast cancer cells, whereas breast cancer cells undergoing EMT exhibit loss of BMP6 expression due to methylation of DNA sequences on the BMP6 gene." (PMID 29729076, 2018). "We also found that treatment of aggressive MDA-MB-231 cells with BMP6 resulted in increased cell attachment in co-culture with endothelial cells and aggregation of breast cancer cells near the zebrafish circulation at the expense of single cell invasion." (PMID 27113436, 2016). "This striking difference between ER+ and ER- breast cancer is in line with previous findings on BMP6 expression." (PMID 27113436, 2016). "BMP6 has also been identified as a potential tumour suppressor associated with differentiation and metastasis, which reverses EMT in breast cancer by restoring E-cadherin expression." (PMID 26664652, 2015). "miR-215 also inhibited the expression of BMP-6 through the BMP-6/miR-192 pathway to increase cell proliferation in breast cancer." (PMID 26317904, 2015).
breast cancer (continued). "Three of the breast cancer cell lines demonstrated up-regulation of BMP6 in response to 1,25(OH)2D3 0.5nM however, the group response was not statistically significant." (PMID 23497279, 2013). "The TGF-β family members, including TGF-β and BMP-6, are reported to alter δEF1 levels and exert their function in the regulation of breast cancer progression and metastasis." (PMID 23285017, 2012). "In the serum samples, promoter hypermethylation of some studied genes was correlated with clinical parameters (APC with histological grade G2; TIMP3 with late stage of breast cancer; BMP6, CST6, and TIMP3 with lymph node involvement)." (PMID 21283676, 2011). "Together, our results are thus compatible with a scenario in which BMP-6 plays a major role in the formation of bone in mammary tumors, a finding that is in line with previous other reports." (PMID 19771160, 2009). "We conclude that the specific BMP expression repertoire differs substantially between different types of mammary tumors and that BMP-6 expression most probably has a biological role in bone formation of canine mammary tumors." (PMID 19771160, 2009). "After establishing the relationship between BMP-6, E-cadherin, and δEF1 in cancer cell lines, we moved on to validate this finding in breast cancer tissue samples." (PMID 17997862, 2007). "In this study, we have determined that BMP-6 is a novel stimulus of E-cadherin expression in breast cancer cells, providing evidence for a potential role of BMP-6 in tumor progression and metastasis." (PMID 17997862, 2007). "In the current study, we have uncovered that one of these factors, BMP-6, contributes to the regulation of E-cadherin-mediated epithelial-mesenchymal transition of breast cancer in vitro." (PMID 17997862, 2007). "We conclude that repression of δEF1 plays a key role in mediating BMP-6-induced transcriptional activation of E-cadherin in breast cancer cells." (PMID 17997862, 2007). "The inverse relationship between BMP-6/E-cadherin and δEF1 were validated in 16 breast cancer specimens using quantitative RT-PCR." (PMID 17997862, 2007). "In that study, we observed significantly lower levels of BMP-6 mRNA in ER- breast cancer cells compared with ER+ breast cancer cells, an effect attributed to hypermethylation status in the ER- breast cancer cells." (PMID 17997862, 2007). "In 16 breast cancer specimens, the inverse correlation between BMP-6/E-cadherin and δEF1 was observed in both ER+ cases (4 of 8 cases) and ER- cases (7 of 8 cases)." (PMID 17997862, 2007). "Higher levels of BMP-6 and E-cadherin transcripts were observed in ER+ breast cancer cells, while lower amounts were detected in ER- cells." (PMID 17997862, 2007). "This coincides with our previous finding that BMP-6 promoter methylation status is correlated with ER status in breast cancer." (PMID 17997862, 2007). "Our data suggest that the stimulatory effect of BMP-6 on E-cadherin transcription in breast cancer cells occurs indirectly, through the reduced expression and activity of δEF1." (PMID 17997862, 2007). "MCF-7 breast cancer cells, an ER+ cell line that expressed high levels of BMP-6 and E-cadherin exhibited very low levels of δEF1 transcript." (PMID 17997862, 2007). "In this communication, we report that BMP-6 up-regulates the expression of E-cadherin at the mRNA level in breast cancer cells, determined by quantitative RT-PCR and luciferase assay." (PMID 17997862, 2007). "Further studies should be focused on better understanding of the signal transduction mechanisms and the relationship between BMP-6 and δEF1 in breast cancer formation, progression, and metastasis." (PMID 17997862, 2007). "As a tumor suppressor gene, low expression of BMP6 led to breast cancer progression." (PMID 36532723, 2022). "However, little is known about how BMP6 expression is regulated and its mechanisms in breast cancer drug resistance." (PMID 36532723, 2022).
breast cancer (continued). "BMP6 also inhibits cell proliferation via downregulation of miR-192 and inhibits stress-induced apoptosis via both Smad and p38 signal pathways in breast cancer cells." (PMID 35646941, 2022). "In this study, we showed that BMP6 was upregulated by TOX3 in KGN cells, which may contribute to the understanding of the roles of TOX3 and BMP6 in the pathogenesis of breast cancer." (PMID 33716953, 2020). "In addition, BMP-6 in breast cancer cells can be upregulated by EGF and other EGFR ligands such as transforming growth factor-α, amphiregulin and betacellulin." (PMID 28733469, 2017). "Since BMP6 is considered to be a tumor suppressor in breast cancer, upregulation of BMP6 in RCC cells may contribute to attenuated cell growth of RCC4 and A498 cells compared to that of the nonmalignant cell line RC-124." (PMID 28775934, 2017). "Several studies have reported BMP6 as a potential negative regulator of breast cancer progression." (PMID 27113436, 2016). "BMP6 expression is downregulated in aggressive ER- breast cancers." (PMID 27113436, 2016). "BMP-6 has also been shown to inhibit MMP-9 expression in breast cancer cells." (PMID 25897433, 2015). "It has been assumed that demethylation of BMP6 and re-expression of this gene might modulate metastasis and invasion in breast cancer." (PMID 22695536, 2012). "Indeed, investigators have showed that bone morphogenetic protein 6 played its anti-apoptotic effect in breast cancer through activation of p38 pathway." (PMID 19222834, 2009). "Consistent with the fact that higher level of δEF1 expression is associated with more invasive phenotype of breast cancer cells, our collective data suggests that δEF1 is likely the switch through which BMP-6 restores E-cadherin-mediated cell-to-cell adhesion and prevents breast cancer metastasis." (PMID 17997862, 2007). "Our results provide the first evidence, at the cellular level, to support the hypothesis that breast cancers may progress and metastasize through the regulation of E-cadherin expression by BMP-6 and δEF1." (PMID 17997862, 2007). "Interestingly, ectopic expression of δEF1 was able to block BMP-6-induced transactivation of E-cadherin, whereas RNA interference-mediated down-regulation of endogenous δEF1 in breast cancer cells abolished E-cadherin transactivation by BMP-6." (PMID 17997862, 2007). "In addition to breast cancer, BMP-6 has been found in a variety of other cancer cell types, including prostate, kidney, esophagus, and osteosarcoma, suggesting its association with the progression of tumorigenesis." (PMID 17997862, 2007). "We recently showed that BMP-6 in ER+ breast cancer cells could be activated by estrogen through promoter demethylation." (PMID 17997862, 2007). "Together, these data suggest a strong inverse relationship between the expressions of BMP-6/E-cadherin and δEF1, which could contribute to the invasiveness and metastatic capacity of breast cancer cells." (PMID 17997862, 2007). "However, further studies will be required for a better understanding of the signal transduction mechanisms regulated by BMP-6 and δEF1 in breast cancer cells." (PMID 17997862, 2007). "In addition, the down-regulation of BMP6 enhanced the drug resistance of breast cancer cells." (PMID 36532723, 2022). "Interestingly, such positive correlations were not unique to the basal‐B group of breast cancer cells, but could be identified in basal‐A and luminal breast cancer cells, suggesting that Snail1 may regulate BMP6 expression in a large cohort of breast cancers." (PMID 29729076, 2018). "In addition, BMP-6 promoter methylation status correlates with ER status in breast cancer." (PMID 28733469, 2017). "Analysis of breast cancer patient data revealed that BMP2 and BMP6 were significantly downregulated in tumors." (PMID 38731813, 2024).